MIR22HG (MIR22 host gene)
Diseases named in the same sentence as MIR22HG in open-access papers (continued):
Sharing a sentence is not in itself a finding about the gene and the disease.
osteosarcoma (1 paper, 2021). A usually aggressive malignant bone-forming mesenchymal neoplasm, predominantly affecting adolescents and young adults. "Specifically, overexpressed MIR22HG is an lncRNA low-expressed in osteosarcoma, which is associated with the suppressed viability and proliferation and the promoted apoptosis of osteosarcoma cells, the effects of which are associated with the regulation on miR-629-5p/TET3 axis." (PMID 34373436, 2021). "As far as we are concerned, the role of MIR22HG in osteosarcoma is confirmed in this study for the first time." (PMID 34373436, 2021). "In the current study, MIR22HG shares the binding sites with miR-629-5p, a miRNA whose expression is upregulated in osteosarcoma, and further results from Pearson’s correlation test suggests the negative correlation between miR-629-5p and MIR22HG." (PMID 34373436, 2021). "Furthermore, it can be concluded that the effects of MIR22HG on osteosarcoma cells are achieved by targeting miR-629-5p, which further completes the discoveries on the roles of both MIR22HG and miR-629-5p in osteosarcoma." (PMID 34373436, 2021). "Previous studies found that MIR22HG plays a tumor suppressor role in a variety of cancers, but its role and mechanism in osteosarcoma are unknown." (PMID 34373436, 2021). "MiR-629-5p could competitively bind with and was negatively correlated with MIR22HG, the latter of which was evidenced by the high expression of miR-629-5p and low expression of MIR22HG in osteosarcoma tissues." (PMID 34373436, 2021). "This study proves the implication of MIR22HG in osteosarcoma, suggesting that MIR22HG may be used as a potential suppressor for osteosarcoma in clinical practice in the future." (PMID 34373436, 2021). "In conclusion, the discoveries in this study unveil the participation of lncRNA MIR22HG in osteosarcoma, and demonstrate that overexpressed MIR22HG represses the viability and proliferation but promotes the apoptosis of osteosarcoma cells via the miR-629-5p/TET3 axis." (PMID 34373436, 2021). "Consequently, it can be assumed that overexpressed MIR22HG might suppress the viability and proliferation but promote apoptosis in osteosarcoma cells." (PMID 34373436, 2021).
Parkinson disease (1 paper, 2024). A progressive degenerative disorder of the central nervous system characterized by loss of dopamine producing neurons in the substantia nigra and the presence of Lewy bodies in the substantia nigra and locus coeruleus. "Importantly, the genes SATB1, MIR22HG, and GBA (red stars) are associated with Parkinson's disease." (PMID 38303548, 2024).
prostate carcinoma (1 paper, 2023). A carcinoma that arises from epithelial cells of the prostate gland. "MIR22HG may acts as a potential biomarker in case of prostate cancer diagnosis." (PMID 37025585, 2023). "On the other hand, LINC00893, LINC01679, MIR22HG, RP1-59D14.5, MAGI2-AS3, NXTAR, FGF14-AS2 and ADAMTS9-AS1 are among lncRNAs that act as tumor suppressors in prostate cancer." (PMID 37025585, 2023).
Sepsis (1 paper, 2024). Sepsis is defined as life-threatening organ dysfunction caused by a dysregulated host response to infection. "In this study, we investigated the effect of Mir22hg on sepsis progression mediated by ferroptosis through in vivo animal models and in vitro cellular models." (PMID 38842666, 2024). "To further validate the function of Mir22hg in sepsis, we induced sepsis in mice with LPS, followed by injection of ad-NC or ad-sh-Mir22hg via tail vein." (PMID 38842666, 2024). "Here, we discovered that Mir22hg knockdown attenuated LPS-induced sepsis by decreasing ferritinophagy-mediated ferroptosis in LPS-induced mouse sepsis models as well as in LPS-induced MLE-12 cells." (PMID 38842666, 2024). "A previous study revealed that Mir22hg is highly expressed in a mouse model of sepsis, but studies confirmed the action of Mir22hg in sepsis have not been discovered." (PMID 38842666, 2024). "Mir22hg contributed to in ferritinophagy-mediated ferroptosis in sepsis via recruiting the m6A reader YTHDC1 and strengthening Angptl4 mRNA stability, highlighting that Mir22hg may be a potential target for sepsis treatment based on ferroptosis." (PMID 38842666, 2024). "This study utilized lipopolysaccharide (LPS) to produce in vivo and in vitro models of sepsis to elucidate whether Mir22hg participates in the severity of sepsis by mediating ferritinophagy-mediated ferroptosis." (PMID 38842666, 2024). "The long non-coding RNA Mir22hg is involved in the regulation of ferroptosis and aberrantly overexpression in lipopolysaccharide (LPS)-induced sepsis mice, but whether it regulates sepsis through ferritinophagy-mediated ferroptosis is unclear." (PMID 38842666, 2024). "So, we explored whether Mir22hg is involved in sepsis by regulating ferritinophagy-mediated ferroptosis." (PMID 38842666, 2024). "In conclusion, Mir22hg was able to recruit the m6A reader YTHDC1 to stabilize Angptl4 mRNA expression, thereby promoting ferritinophagy to accelerate sepsis progression." (PMID 38842666, 2024).
triple-negative breast carcinoma (1 paper, 2023). An invasive breast carcinoma which is negative for expression of estrogen receptor (ER), progesterone receptor (PR), and human epidermal growth factor receptor 2 (HER2). "Notably, represses ADSL expression and inhibits the long noncoding RNA MIR22HG to regulate the proliferation and invasion of triple-negative breast cancer cells." (PMID 37976135, 2023).
tumor (28 papers, 2015 to 2024). "We identified that TNM stage (P=0.016), tumor number (P=0.012), AFP>400 (ng/ml) (P=0.008), MVI (P=0.024), tumor size (P<0.001) and under-expression of MIR22HG (P=0.021) were significant prognostic factors associated with HCC patients." (PMID 29371967, 2017). "Importantly, the aberrant expression of MIR22HG is significantly associated with important clinical characteristics, such as advanced tumor size, stage, TNM stage and overall survival in various kinds of human cancer." (PMID 33267888, 2020). "Abnormal expression of MIR22HG is associated with a variety of tumours." (PMID 31613058, 2019). "MIR22HG exerts its tumor-suppressive effects through various mechanisms, including the suppression of proliferation, invasion, and metastasis, and the attenuation of CSC-activating NOTCH2 signaling." (PMID 38800385, 2024). "By competing with SMAD2 (Recombinant Mothers Against Decapentaplegic Homolog 2) and modifying the TGF pathway’s activity, MIR22HG was able to exhibit its tumor suppressor effect." (PMID 38110999, 2023). "The tumor suppression function of MIR22HG has been described in hepatocellular carcinoma, colorectal cancer, and glioblastoma." (PMID 34446703, 2021). "The long noncoding RNA called MIR22 host gene (MIR22HG) was previously identified as a tumor suppressor in several cancers." (PMID 34446703, 2021). "Silencing of MIR22HG promoted cell survival, proliferation and tumor metastasis in vitro and in vivo." (PMID 32127004, 2020). "Analysis of TCGA dataset revealed the up-regulation of MIR22HG in GBM tissues compared with non-tumor tissues (11.06 vs. 7.51)." (PMID 32500915, 2020). "Taken together, these results suggested that MIR22HG plays tumor suppressor role by affecting colony formation, proliferation and cell migration." (PMID 32127004, 2020). "Collectively, these results demonstrated that MIR22HG exerted its tumor suppressive function through competitively binding to SMAD2, thereby preventing the interaction between SMAD2 and SMAD4 in CRC cells." (PMID 32127004, 2020). "The differential expression of MIR22HG in BC was further explored by measuring its expression levels in both BC and non-tumor tissues from the 58 patients included in the present study." (PMID 32500915, 2020). "Mechanistically, MIR22HG exerts its tumor suppressive activity by competitively interacting with SMAD2 and modulating the activity of TGFβ pathway." (PMID 32127004, 2020). "We systematically investigated the expression pattern of lncRNAs and revealed MIR22HG acts as a tumor suppressor in CRC." (PMID 32127004, 2020). "Functionally, MIR22HG silencing has diminished cell proliferation, invasion and tumor growth in xenograft models." (PMID 33634032, 2020). "MIR22HG was first reported by Torimura et al44 and is commonly down‐regulated in tumour tissues and participates in the inhibition of cell proliferation." (PMID 31613058, 2019). "From these previous studies, we can consider that MIR22HG is closely related to the prognosis of the tumour." (PMID 31613058, 2019). "Investigation of the molecular mechanisms by which MIR22HG contributes to tumor suppression identified the involvement of HuR, which is known to regulate the splicing, stability, or translation of thousands of both coding and non-coding RNAs." (PMID 29371967, 2017). "Moreover, the genome-wide expression profile revealed that the tumor-suppressor gene MIR22HG was highly elevated, with a 4.4 log-fold increase under μg." (PMID 38255998, 2024). "However, MIR22HG plays tumor-suppressive role in various other types of cancer, including lung cancer, hepatocellular carcinoma, endometrial cancer, gastric cancer, and cholangiocarcinoma." (PMID 38800385, 2024). "Moreover, the authors reported that low MIR22HG expression was related to tumor size (P = 0.015), TNM stage (P = 0.022) and poor overall survival (P = 0.030) by qRT-PCR detection." (PMID 33267888, 2020).
tumor (continued). "All these data demonstrated that down-regulation of MIR22HG in CRC may play a tumor suppressor role and could serve as a novel prognostic marker." (PMID 32127004, 2020). "Although these results suggest that MIR22HG might play a tumor-suppressor role in cancer, little is known about the regulation of MIR22HG." (PMID 32127004, 2020). "Our preliminary bioinformatics analysis showed that miR-486 may bind with MIR22HG, a tumor suppressive long (>200 nt) non-coding RNA (lncRNA) in different types of cancer." (PMID 32500915, 2020). "The tumor suppressive role of MIR22HG has been studied in several types of cancer." (PMID 32500915, 2020). "Furthermore, we examined the effect of MIR22HG overexpression on tumor growth in vivo using mouse subcutaneous xenograft models." (PMID 32127004, 2020). "Moreover, under-expression of MIR22HG was closely related to tumor encapsulation, microvascular invasion (MVI), and TNM stage." (PMID 29371967, 2017). "Moreover, under-expression of MIR22HG was correlated with tumor progression and was found to be an independent predictor for the prognosis of patients with HCC after curative resection." (PMID 29371967, 2017). "Overall, according to the network, MIR22HG regulates FXYD domain‐containing ion transport regulator 3 (FXYD3) through hsa‐mir‐613 and hsa‐mir‐24‐3p, and its downregulation may be associated with tumor formation." (PMID 38321787, 2024). "Moreover, our results demonstrate that tumor suppressor MIR22HG may act as a clinical biomarker and overexpression of MIR22HG may be a novel synergistic strategy for enhancing immunotherapy sensitivity, thereby enhancing its clinical benefits for CRC patients." (PMID 32127004, 2020). "Moreover, MIR22HG has been reported to function as a competitive endogenous RNA (ceRNA), be involved in signaling pathways, interact with proteins and interplay with miRNAs as a host gene to participate in tumorigenesis and tumor progression." (PMID 33267888, 2020). "For instance, MIR22HG has been demonstrated to promote CD8 T-cell infiltration and acts as a tumor suppressor in cancer." (PMID 35603200, 2022). "LINC00900, MIR210HG, MIR22HG, PVT1, and SNHG18 expression increased, whereas HAR1A, LINC00641, SLC25A21-AS1, and SNAI3-AS1 expression decreased with tumor grade." (PMID 34288803, 2021). "Liu and Wu previously found that miR-22-3p and its host gene MIR22HG are down-regulated in HCC tissues and play a role as tumor suppressor genes." (PMID 33718133, 2021). "We observed that knockdown of MIR22HG significantly decreased the migration and invasion potential in OE33 and FLO-1 cells, indicating that MIR22HG may have a role in EAC metastasis or tumor progression." (PMID 31291201, 2019).
cancer (23 papers, 2013 to 2024). A tumor composed of atypical neoplastic, often pleomorphic cells that invade other tissues. "One such example is MIR22HG, a cancer-causing lncRNA that has been identified as highly deregulated in GBM through the analysis of accessible datasets." (PMID 39553554, 2024). "As a recently-indentified lncRNA, MIR22HG was found to be associated with the onset and progression of many cancers." (PMID 34187303, 2021). "Various mechanisms have been implicated in the MIR22HG-mediated regulation of cancer progression; for example, MIR22HG has been reported to function as a competitive endogenous RNA (ceRNA), be involved in signaling pathways, interact with proteins and interplay with miRNAs as a host gene." (PMID 33267888, 2020). "We found that the genomic region of MIR22HG shows prevalent CNV loss across cancer types." (PMID 32127004, 2020). "Considering the differential expression and significant biological function of MIR22HG, it may have great value for diagnostic, prognostic, and therapeutic cancer research." (PMID 33267888, 2020). "The involvement of MIR22HG in the Wnt/β-catenin signaling pathway has been widely acknowledged, highlighting its significance in this particular cancer type." (PMID 39553554, 2024). "MIR22HG expression is elevated in many human cancers and is involved in many signaling pathways by acting as a competitive endogenous RNA, such as cell proliferation and apoptosis pathways." (PMID 37081883, 2023). "As a host gene involved in the development and spread of cancer, MIR22HG has been demonstrated to exhibit competitive endogenous RNA (ceRNA) behavior, take part in signaling networks, and interact with proteins and miRNAs." (PMID 36276869, 2022). "Particularly, liver metastasis patients were also with lower expression of MIR22HG as compared with their own primary cancer (p < 0.001)." (PMID 32127004, 2020). "Up-to-date studies have provided a comprehensive overview showing that MIR22HG is recognized as a regulator of cancer-influencing proliferation, apoptosis, and migration." (PMID 33267888, 2020). "We found that MIR22HG was significantly low expressed in cancer as compared with normal controls (p < 0.001)." (PMID 32127004, 2020). "The biological function of MIR22HG in cancer will need to be explored in more detail, and its possible relevance to cancer therapeutic targets will also need to be examined." (PMID 33267888, 2020). "By analyzing the TCGA dataset, we observed down-regulation of MIR22HG in most types of cancer including BC." (PMID 32500915, 2020). "Future investigations will be necessary to explore the precise molecular regulatory mechanisms of MIR22HG in carcinogenesis and cancer progression to translate MIR22HG from basic research into the clinic as early as possible." (PMID 33267888, 2020). "Our data provide mechanistic insights into the regulation of MIR22HG in TGFβ pathway and facilitates immunotherapy in cancer." (PMID 32127004, 2020). "Growing evidence suggests that the MIR22HG-mediated dysregulation of signaling pathways is central to many different types of cancer." (PMID 33267888, 2020). "We found that the co-expressed genes of MIR22HG are significantly enriched in number of cancer-related signaling pathways, including IL6-JAK-STAT3, TNFA signaling and TGFβ signaling pathway." (PMID 32127004, 2020). "In this study, we first showed MIR22HG, which has been demonstrated to be involved in the progression of several cancer types, played an important role in regulating BMSC osteogenesis." (PMID 32732881, 2020). "Decreased MIR22HG expression is associated with increased expression levels of MET and p21 oncogenes and cancer cell survival via its impact on YBX1 protein stability." (PMID 32760219, 2020).
cancer (continued). "Many previous studies revealed that MIR22HG exhibited tumor-suppressive role in several types of cancer including lung cancer, hepatocellular carcinoma, endometrial cancer, gastric cancer and cholangiocarcinoma, and its low expression was associated with poor prognosis." (PMID 32732881, 2020). "Overwhelming evidence supports the proproliferative and antiapoptotic roles of MIR22HG in cancer." (PMID 33267888, 2020). "Previous studies have characterized MIR22HG in different types of cancer." (PMID 32500915, 2020). "Given the differential expression of MIR22HG in cancer, MIR22HG might be a novel biomarker for cancer diagnosis and prognosis." (PMID 33267888, 2020). "Therefore, in-depth research on the roles of MIR22HG in different tumors and its possible mechanisms of action will provide new insight into clinical cancer treatment." (PMID 33267888, 2020). "Two independent studies examined whether MIR22HG functions as the host gene of miR-22 in cancer progression." (PMID 33267888, 2020). "In addition, MIR22HG exhibits extensive mechanistic diversity to carry out its functional roles; therefore, it may represent a novel target to overcome cancer." (PMID 33267888, 2020). "In the case of hsa-miR-17-5p and hsa-miR-20b-5p, which interacted with MIR22HG (ENST00000334146), 39.5% of the 38 enriched pathways were related to cancer." (PMID 38027526, 2023). "Numerous lncRNAs, such as NEAT1, UCA1, MIR22HG, and LINK-A, have involved in immune regulation in cancer." (PMID 36071454, 2022). "Regardless of the important roles of MIR22HG in cancer progression, studies involving the roles of MIR22HG in OA were still lacking." (PMID 34187303, 2021).
cardiovascular disease (1 paper, 2022). "In summary, the relationship betweenGAS5 and H19 and cardiovascular disease is relatively clear,but the relationship among MIR22HG, LINC01091, andcardiovascular disease requires further study." (PMID 39077137, 2022).
MIR22HG also shares sentences with these, for which no sentence is quoted: ovarian carcinoma (3 papers); cholangiocarcinoma (2); infection (1); latent infection (1); liver fibrosis (1); lymph node metastasis (1); ovarian tumors (1); rectal cancer (1); serous ovarian cancer (1).